CCM2 (CCM2 scaffold protein)
Description:
Component of the CCM signaling pathway which is a crucial regulator of heart and vessel formation and integrity. May act through the stabilization of endothelial cell junctions (By similarity). May function as a scaffold protein for MAP2K3-MAP3K3 signaling. Seems to play a major role in the modulation of MAP3K3-dependent p38 activation induced by hyperosmotic shock (By similarity).
Synonyms: C7orf22; PP10187; MGC4607; OSM
Tractability: PROTAC: ubiquitination databases record sites on it; its protein half-life has been measured.
Gene: Protein-coding gene on chromosome 7 (44,999,475 to 45,076,469, forward strand). Ensembl gene ENSG00000136280.
Subcellular location: Cytoplasm
Subcellular location (Human Protein Atlas): Mitochondria
Gene Ontology:
Molecular function: protein binding
Biological process: endothelial tube morphogenesis; vasculogenesis; endothelium development; heart development; integrin-mediated signaling pathway; regulation of angiogenesis; stress-activated MAPK cascade
Cellular component: cytoplasm; mitochondrion; protein-containing complex
Genetic constraint (gnomAD): Loss-of-function variants: 22 observed, 41.74 expected, observed/expected ratio (o/e) 0.53, 90% interval 0.38 to 0.75. The upper end of that interval is the gene's LOEUF score, 0.75, which puts it in group 3 of 6, group 1 being the genes least tolerant of losing a copy. Missense variants: 481 observed, 600.96 expected, observed/expected ratio (o/e) 0.8, 90% interval 0.74 to 0.86. Synonymous variants: 218 observed, 250.27 expected, observed/expected ratio (o/e) 0.87, 90% interval 0.78 to 0.98.
Gene-disease validity (ClinGen):
ClinGen rates the evidence that CCM2 causes each of these diseases.
cerebral cavernous malformation 2 (autosomal dominant): Definitive.
Homologues: Orthologues: macaque CCM2 (99% identical), chimpanzee CCM2 (98% identical), mouse Ccm2 (93% identical), rat Ccm2 (92% identical), guinea pig CCM2 (91% identical), dog CCM2 (89% identical), tropical clawed frog ccm2 (81% identical), rabbit CCM2 (80% identical), pig CCM2 (76% identical), zebrafish ccm2 (75% identical). Paralogues in human: CCM2L (43% identical).